BDNF (brain derived neurotrophic factor)
Diseases named in the same sentence as BDNF in open-access papers (continued):
Sharing a sentence is not in itself a finding about the gene and the disease.
schizophrenia (continued). "Examples of epigenetic modulations of genes include hypermethylation of genes such as BDNF and FKBP5 found in the brain and blood samples of psychiatric patients suffering from schizophrenia, major depression, bipolar disorder, and post-traumatic stress disorders." (PMID 35631466, 2022). "The same results were obtained in this study, suggesting that the rs11030101 locus of the BDNF gene plays an important role in the occurrence of clinical negative symptoms of schizophrenia, which provides some clues for clinical diagnosis." (PMID 35368680, 2022). "In studies on the effectiveness of cognitive training in a group of people with schizophrenia, the level of BDNF was not in every case significantly different from that recorded in the healthy population." (PMID 36672535, 2022). "Further longitudinal and prospective investigations may offer new venues for exploring the relationship between serum BDNF levels and depressive symptoms in patients with FEDN schizophrenia." (PMID 35757201, 2022). "Our study showed that schizophrenia patients with depressive symptoms had higher serum BDNF levels than those without depressive symptoms, which is consistent with previous studies, but contradicts the findings of some investigations." (PMID 35757201, 2022). "BDNF rs6265 196 G > A and MMP-9 rs3918242–1562C > T SNPs are related to the clinical features of schizophrenia and could be a useful biomarker for the changes, remission or deterioration of clinical status of schizophrenia." (PMID 36325525, 2022). "In conclusion, BDNF levels were shown to be higher in the serum of patients with FEDN schizophrenia with depressive symptoms than in those without." (PMID 35757201, 2022). "In the current study, the distribution of BDNF SNP genotypes (rs11030101, rs2030324, and rs6265) was not different between healthy controls and patients with schizophrenia, which is in accordance with the results of previous studies." (PMID 35368680, 2022). "A study protocol has been reported for measuring BDNF levels in schizophrenia patients undergoing yoga therapy, but results have not yet been published." (PMID 34220575, 2021). "Serum levels of BDNF, GDNF and NGF in schizophrenia patients have been evaluated previously." (PMID 34763683, 2021). "Their results suggest that BDNF levels were correlated with EF measured by verbal fluency tests (VFT) and WCST and that BDNF was involved in the pathophysiology of EF impairments in patients with chronic schizophrenia." (PMID 34207545, 2021). "The authors suggested that the increase of BDNF levels and better cognitive performance, particularly delayed memory, may be related to the pathophysiological process of T2DM in chronic schizophrenia patients." (PMID 34220575, 2021). "In addition, in another model of schizophrenia in rats with a neonatal ibotenic lesion of the ventral HIP, a reduction in the level of BDNF mRNA in the PFC and HIP was demonstrated." (PMID 34201038, 2021). "One might expect that the plasma membrane expression of NHE5 should be low in schizophrenia with hypofunction of NMDA receptors and BDNF levels should be elevated." (PMID 34445065, 2021). "BDNF, GDNF, NGF and Klotho levels were lower in schizophrenia patients than in healthy controls." (PMID 34763683, 2021). "In contrast to the initial findings, we did not observe any changes for IL-6, TNFα and glucose in schizophrenia, nor for BDNF and IL-6 in MDD." (PMID 33653423, 2021). "Considering that recently some research projects are no longer studying categorial diagnoses such as schizophrenia, but syndromes such as psychosis, it is important to update the review of the relationship between BDNF and cognition in psychotic patients." (PMID 34220575, 2021). "They found that schizophrenia patients with T2DM had significantly higher serum BDNF levels than schizophrenia patients without T2DM." (PMID 34220575, 2021).
schizophrenia (continued). "In this study, the hypothesis that the blood serum levels of BDNF, GDNF, NGF and Klotho in schizophrenia patients and healthy controls would be related to cognitive functions was investigated." (PMID 34763683, 2021). "Additionally, meta-analyses showed that blood BDNF and NGF levels were significantly decreased in schizophrenia patients when compared with controls." (PMID 33420109, 2021). "Several studies have investigated the relationship between non-pharmacological interventions and peripheral BDNF levels in patients with schizophrenia." (PMID 34220575, 2021). "Significant negative correlations between BDNF serum levels and FA values in schizophrenia patients were detected in the right inferior fronto-occipital fasciculus and the right superior longitudinal fasciculus." (PMID 32153434, 2020). "In conclusion, there is a great potential for BDNF, GMF-β, and the 115-kDa isoform of RAB3GAP1 proteins to act as possible biomarkers of schizophrenia, and they may even differentiate early stages (e.g. BDNF) from later stages (e.g. GMF-β) of the disease." (PMID 31849731, 2019). "We hypothesize that current levels of PA (steps per day and MVPA) will be positively associated with cognition in this sample of individuals with schizophrenia, with CRF and/or BDNF mediating the relationship between PA and cognition." (PMID 31708824, 2019). "In conclusion, GMF-β, BDNF, and 115-kDa isoform of RAB3GAP1 showed significantly reduced levels in plasma of patients with schizophrenia, thus making them potential biomarkers in schizophrenia." (PMID 31849731, 2019). "One study has shown that cognitive remediation leads to an increase in BDNF in individuals with schizophrenia; however, this was not replicated in a slightly larger sample." (PMID 31708824, 2019). "Significant differences of serum BDNF levels were found between male patients with schizophrenia with and without metabolic syndrome, but not in females." (PMID 28562580, 2017). "Using analysis of covariance adjusted for age and body mass index, male patients with schizophrenia with metabolic syndrome had higher serum BDNF levels than those without (4.6 ± 4.7 vs 3.3 ± 3.8 ng/mL, P = .022)." (PMID 28562580, 2017). "32,33However, the benefits of exercise in schizophrenia cannot be attributed to BDNF alone, given the lack of available data examining other potential mechanisms." (PMID 27521348, 2017). "Serum BDNF levels seem to be one of the indicators of schizophrenia and its progress; nevertheless, we still do not have sufficient information about this neurotropic factor." (PMID 29287075, 2017). "Furthermore, they observed that learning deficits and cognitive flexibility improved in treated animals, and thus found a correlation between the expression level of BDNF and NMDA and the symptoms of schizophrenia." (PMID 29246029, 2017). "In male patients with schizophrenia, ones with metabolic syndrome have significantly higher serum BDNF levels than ones without." (PMID 28562580, 2017). "The major finding of this study is the gender difference of BDNF levels between ones with and without metabolic syndrome among patients with schizophrenia." (PMID 28562580, 2017). "We aimed to investigate the serum BDNF levels in patients with schizophrenia with and without metabolic syndrome." (PMID 28562580, 2017). "In this study, significant difference of serum BDNF levels were found between male patients with schizophrenia with and without metabolic syndrome, but not in females." (PMID 28562580, 2017). "Several studies have investigated the relationship between non-pharmacological interventions (NPIs) and peripheral brain-derived neurotrophic factor (BDNF) in schizophrenia patients." (PMID 27783051, 2016).
schizophrenia (continued). "On the other hand, several trials assessing the alterations in peripheral BDNF after non-pharmacological interventions (NPIs) in schizophrenia have been conducted." (PMID 27783051, 2016). "For example, aside from these three interventions, 8-week sulforaphane (SFN) supplementation therapy was found to improve some domains of cognitive function in schizophrenia, while no significant change in serum BDNF levels was found." (PMID 27783051, 2016). "Schizophrenia and MDD also inhibit other important neuroplastic mechanisms such as synaptic plasticity and BDNF expression within the hippocampus." (PMID 27524962, 2016). "Second, the role of hippocampal astroglial BDNF signaling in the pathophysiology of this schizophrenia model was not directly examined." (PMID 26700309, 2015). "There are limited data on diet and hippocampal-related parameters in humans; however, adults with schizophrenia who were undertaking a regime of dietary improvement for at least 4 weeks had higher serum levels of BDNF than those in the no diet condition." (PMID 26349802, 2015). "Similarly, there are consistencies regarding changes in BDNF signaling in the animal model of schizophrenia based on antagonism of NMDA receptors, as both decreased BDNF protein levels in the hippocampus and elevated BDNF have been reported." (PMID 26700309, 2015). "There were no strong, significantcorrelations between plasma BDNF levels and activation in any of the six ROIs in peoplewith schizophrenia." (PMID 25162472, 2015). "Interestingly, postmortem studies have reported alterations in BDNF, NRG1 and their receptors in prefrontal cortex of schizophrenia subjects indicating their roles in the pathophysiology of this disorder." (PMID 25052836, 2014). "In addition, incubation with BDNF decreased release of NO from the activated microglia, suggesting that BDNF might have an anti-inflammatory effect through the inhibition of microglial activation and could be useful for the treatment of neuropsychiatric disorders including schizophrenia." (PMID 25414641, 2014). "Specifically, BDNF mRNA levels were significantly decreased in layers IV and V of DLPFC in schizophrenia, in layer VI of ACC in schizophrenia and MDD and in layer VI of ITG in schizophrenia, BPD and MDD." (PMID 24802307, 2014). "Therefore, alterations in BDNF may contribute to altered brain development, failures in neuroplasticity, and synaptic disconnectivity, and explain at least in part some of the morphological, neurochemical, and cytoarchitectonic abnormalities found in the brains of patients with schizophrenia." (PMID 23785335, 2013). "Recently, BDNF and its high-affinity receptor, NTRK2, widely expressed in the adult brain, were both reported decreased in human postmortem of schizophrenia suggesting they were involved in pathophysiology of schizophrenia." (PMID 24069289, 2013). "BDNF HETs may be a valuable model for further research into the effects of BDNF signaling in PPI brain circuits, and particularly sex-differences, which may contribute to sensorimotor gating deficits in patients with schizophrenia." (PMID 23781174, 2013). "A recent review of serum BDNF levels in patients with a first psychotic episode shows a significant decrease in patients with schizophrenia but not in those with non-schizophrenia psychosis." (PMID 23320462, 2013). "In neurons, BDNF-mediated mutual upregulation of GluR2 and GRIP1 can have considerable implications for the effects of the neurotrophin to offset schizophrenia and behavioral depression and promote memory maintenance and synaptic potentiation during late phase LTP (l-LTP)." (PMID 23460828, 2013). "We have also previously demonstrated that risperidone did not change serum brain-derived neurotrophic factor (BDNF) levels in patients with schizophrenia." (PMID 22269819, 2012).
schizophrenia (continued). "Overall, the majority of research on BDNF has focused on memory function and for COMT on measures of executive skills and working memory in healthy controls and individuals with neuropsychiatric disorders (e.g., schizophrenia-spectrum and bipolar disorders)." (PMID 23087644, 2012). "They found significant evidence for a gene x environment interaction in V-akt murine thymoma viral oncogene homolog 1 (AKT1), brain-derived neurotrophic factor (BDNF), dystrobrevin binding protein 1 (DTNBP1), and glutamate receptor metabotrophic (GRM) genes in developing schizophrenia." (PMID 20046382, 2009). "The expression of BDNF and Spry2 was examined by quantitative real-time PCR (qRT-PCR) in the Stanley Array Collection, derived from dorsolateral prefrontal cortex (DLPFC) of individuals with schizophrenia, bipolar disorder, or psychiatrically normal controls." (PMID 18335055, 2008). "Gene expression of BDNF and NURR1 mRNA in the midbrain was found to negatively correlate with duration of illness in schizophrenia cases, and this may reflect that both mRNAs are known to decrease with age, and the effect of increasing age on the brain may be more accelerated in schizophrenia." (PMID 40335479, 2025). "However, schizophrenia patients are unable to produce sufficient amounts of BDNF to mitigate the inflammatory damage induced by IL-259, and a negative correlation between BDNF and IL-2 levels was observed in our study." (PMID 40133606, 2025). "Other studies suggest that there may be a negative correlation between BDNF concentration and the severity of depressive symptoms in patients with schizophrenia." (PMID 40804390, 2025). "Furthermore, we report that, in patients diagnosed with pharmaco-resistant schizophrenia and treated with clozapine, the negative correlations between IL-1β-BDNF and between the FasL level and leukocyte count are absent." (PMID 41010622, 2025). "The available data on BDNF levels in schizophrenia are not consistent." (PMID 41010622, 2025). "Overall downregulation of BDNF mRNA in the schizophrenia group compared to controls in this study appears to be mostly found in cases in the high inflammatory subgroup, as corresponding reductions in BDNF mRNA are not present in schizophrenia cases with low inflammation." (PMID 40335479, 2025). "The results of this study, which show a correlation between alterations in BDNF and decreased expression of SPRY2, raise the idea that the latter is the result of treatment-related factors rather than important elements in the pathophysiology of bipolar illness or schizophrenia." (PMID 39456824, 2024). "This could suggest that a relative increase in BDNF levels possibly acts as a compensatory response in patients with schizophrenia, although it might not be sufficient to counteract the inflammatory damage caused by increased cytokines like IL-8." (PMID 38793070, 2024). "Among proteins showing the highest enrichment in the mGlu2 interactome, we focused on BDNF/NT-3 growth factor receptor TrkB (also called NTRK2, highlighted in green), given the well-documented influence of the BDNF/TrkB axis on the pathophysiology of schizophrenia." (PMID 38277461, 2024). "The main aim of this systematic review and meta-analysis is to establish whether there is a correlation between the brain-derived neurotrophic factor (BDNF) level and electroconvulsive therapy (ECT) treatment and the reduction in psychotic symptoms in patients diagnosed with schizophrenia." (PMID 37685795, 2023). "Interestingly, there are studies showing a negative correlation between BDNF levels and the severity of depressive symptoms in schizophrenia." (PMID 36979300, 2023). "The aim of this study was to determine the relationship between the levels of selected inflammatory, pro-oxidant and antioxidant markers; initial KP metabolites; BDNF; and symptom severity of the different dimensions of schizophrenia: positive, negative, cognitive and depressive." (PMID 36979300, 2023).
schizophrenia (continued). "While plasma and serum BDNF were correlated in healthy individuals or in drug-free schizophrenia patients, these values may not change in the same direction following treatment." (PMID 37759825, 2023). "Consequently, peripheral BDNF levels as a reliable biomarker for schizophrenia are currently not well-established." (PMID 37520481, 2023). "It has been revealed that serum BDNF levels in the patients treated with clozapine are higher than those treated with risperidone or typical antipsychotics, However, it has been shown that serum levels of BDNF of patients with schizophrenia do not raise after antipsychotic treatment." (PMID 37485797, 2023). "This is supported by studies that show a correlation between BDNF levels and its signal in many neuropsychiatric diseases, a correlation between reduced BDNF levels and the development of schizophrenia, and a negative correlation between negative and total PANSS scores and serum BDNF levels." (PMID 37190616, 2023). "First, most studies were not designed to test the hypothesis that BDNF levels may help schizophrenia diagnosis or predict treatment response." (PMID 35447946, 2022). "In addition, genetic interactions between BDNF and catechol-o-methyl transferase (COMT), the enzyme responsible for dopamine and norepinephrine degradation, translate into cognitive and behavioral alterations and impact schizophrenia symptoms." (PMID 35955546, 2022). "However, the same authors showed that decreased BDNF levels did not play a major role in cognitive dysfunction in most patients with schizophrenia." (PMID 35163141, 2022). "Our findings also suggest that, although short-term aerobic exercise may not improve cognitive performance, it may increase serum BDNF levels in patients with schizophrenia (as seen in the present study)." (PMID 36261468, 2022). "Therefore, the purpose of this study was to determine whether BDNF levels correlated with depressive symptoms in patients with first-episode and drug-naïve (FEDN) schizophrenia." (PMID 35757201, 2022). "In patients with FEP or chronic schizophrenia, future pharmacological and non-pharmacological studies should consider what we know about BDNF, particularly as a biomarker of cognition, in order to guide potential therapeutic strategies for the improvement of cognitive symptoms." (PMID 34220575, 2021). "Furthermore, a positive correlation was found between serum levels of BDNF and serum levels of 5-HT in the schizophrenia group, but not in the healthy control group." (PMID 34393855, 2021). "However, a survey showed that there was no change in serum BDNF in patients with schizophrenia after taking risperidone." (PMID 34234699, 2021). "As we found a negative correlation between BDNF levels and FA maps in schizophrenia patients, it could be consecutive to altered structural connectivity in the SLF as a kind of feedback mechanism." (PMID 32153434, 2020). "Consistent with this hypothesis, strong positive correlations between BDNF protein levels and SST mRNA levels were observed in the PFC of human subjects (post mortem tissue) with schizophrenia, suggesting that BDNF may function to regulate SST expression in the PFC." (PMID 33192369, 2020). "We found a negative correlation between BDNF levels and FA values in the SLF, a fiber tract that connects frontal with temporal and also parietal and occipital regions and has been repeatedly implicated in schizophrenia." (PMID 32153434, 2020). "Furthermore, BDNF levels were positively correlated with abnormal MnSOD activity after adjusting for covariates, consistent with the results of positive correlations between BDNF and TSOD in BD, BDNF, and CuZnSOD in schizophrenia." (PMID 33061913, 2020).